ENSG00000281179 (novel gene identicle to IGHV1OR15-1)
Gene: Immunoglobulin variable (V) gene on chromosome 15 (21,717,808 to 21,718,245, reverse strand). Ensembl gene ENSG00000281179.
Gene Ontology:
Molecular function: antigen binding
Biological process: immunoglobulin mediated immune response
Cellular component: extracellular region; plasma membrane
Homologues: Orthologues: mouse Ighv1-53 (68% identical), mouse Ighv1-64 (68% identical), mouse Ighv1-74 (68% identical), mouse Ighv1-50 (68% identical), mouse Ighv1-55 (67% identical), mouse Ighv1-69 (66% identical), mouse Ighv1-72 (66% identical), mouse Ighv1-26 (64% identical), mouse Ighv1-4 (64% identical), mouse Ighv1-59 (64% identical), mouse Ighv1-62-3 (64% identical), mouse Ighv1-66 (64% identical), and 47 more. Paralogues in human: IGHV1OR15-1 (100% identical), IGHV1-2 (91% identical), IGHV1-3 (86% identical), IGHV1-46 (84% identical), IGHV1-18 (82% identical), IGHV1-45 (80% identical), IGHV1-24 (79% identical), IGHV1-69 (78% identical), IGHV1-69D (78% identical), IGHV1-58 (76% identical), IGHV1-69-2 (76% identical), IGHV1OR21-1 (76% identical), and 66 more.